EZH2 (enhancer of zeste 2 polycomb repressive complex 2 subunit)
Diseases named in the same sentence as EZH2 in open-access papers (continued):
Sharing a sentence is not in itself a finding about the gene and the disease.
cancer (continued). "Our findings serve as a proof-of-concept that activation of histone methyltransferases, such as EZH2, EHMT2, and SMYD3 might promote hepatocarcinogenesis by inducing enhancer aberration of crucial cancer-related genes." (PMID 35300417, 2022). "It should also be noted that evasion of the viral mimicry response is an acquired characteristic of certain cancers, such as acute myeloid leukemia (via SETDB1) and treatment-resistant triple-negative breast cancer (via EZH2), thus evoking new therapeutic vulnerabilities in these malignancies." (PMID 36551854, 2022). "In addition, expression levels of several well-characterized cancer stemness regulators, such as FOXM1 and EZH2, also showed a strong correlation with mRNAsi among the HCC patients of the TCGA-LIHC cohort." (PMID 35158838, 2022). "One of the limitations of experiments related to circRNA/EZH2 axis is the lack of in vivo studies in many cancers." (PMID 35236381, 2022). "The promoting effect of axes HOXA11-AS/miR-124/EZH2 (enhancer of zeste homolog 2 of polycomb group protein), HOXA11-AS/miR-124-3p/ITGB3 (integrin β3), and HOXA11-AS/miR-124/Sp1 (Sp1 transcriptional factor) on cancer cell proliferation, migration, invasion was shown in vitro." (PMID 36362406, 2022). "Furthermore, the overexpression of E2F transcription factor 1 (E2F1), Enhancer of Zeste Homolog 2 (EZH2), and SUZ12 genes have been correlated with progression, migration and invasiveness of cancer." (PMID 34094648, 2021). "Additionally, EZH2, a main PRC2 subunit, was located +219 bp and +441 bp downstream from TSS on the PD-L1 locus only for CD4+ T cells co-cultivated with cancer cells." (PMID 34439305, 2021). "This may be through EZH2, which is positively influenced by TNFα/IL-1β signaling and has been shown to hypermethylate the ODZ4 promoter in cancer, resulting in repressed miR-708 expression." (PMID 33776573, 2021). "Future work is aided by the breadth of literature on G9a function during normal differentiation and development, along with similarities to EZH2, another histone methyltransferase that forms a synthetic lethal relationship with members of the SWI/SNF complex in certain cancers." (PMID 34691767, 2021). "In fact, AKT can inactivate EZH2 by phosphorylation of serine 21 and therefore EZH2 overexpression does not increase PRC2 activity but rather favors the formation of the polycomb repressive complex 4 (PRC4) which is involved in cancer and inflammation." (PMID 34070716, 2021). "Disruption of the bivalent state through inhibition of the H3K27 methyltransferase EZH2 inhibited the self-renewal of cancer cells through de-repression of a key canonical marker of normal colonocyte differentiation, named Indian Hedgehog." (PMID 34523419, 2021). "Moreover, a previous study also demonstrated a link between EZH2 as a regulator of CHK1 phosphorylation in U2OS and HCT116 cancer cells and the DNA damage response." (PMID 33408782, 2021). "As for EZH2, a subunit of the Polycomb repressive complex 2 (PRC2) catalyzing trimethylation of histone H3 lysine 27 (H3K27), it has been shown to induce epithelial-mesenchymal transition (EMT) in several cancer types." (PMID 34790699, 2021). "In addition to the cancer stem cell inhibitors, clinical trials are ongoing with multiple N-Myc, AURKA and BET inhibitors and EZH2 inhibitors (clinicaltrials.gov (accessed on 18 December 2020))." (PMID 33572108, 2021). "Our data also support this hypothesis showing that PTEN depletion, likely through ERG methylation and EZH2 interaction, enhanced trans-activation by ERG/EZH2 complexes in ERG-positive cancer cells." (PMID 34230470, 2021). "Enhancer of zeste homolog 2 (EZH2), a specific histone methyltransferase of histone H3 at Lys 27 (H3K27), has been garnering attention as a prognostic factor as well as an attractive target for cancer therapy." (PMID 35186711, 2021).
cancer (continued). "The study shows that EZH2 dependent protein stability of LSD1, HDAC1, DNMT1, β-catenin, or SMAD2/4, via recruitment of deubiquitinase USP7, is key in suppressing neuronal genes and sustaining the expression of Wnt and TGFβ target genes in cancer cells." (PMID 34552611, 2021). "Both EZH2 and EED degradation by EZH2–EED interactionimpairment (5b) or by EZH2–EED–PROTAC offera significant additional opportunity to block the PRC2 oncogenic activity,above all in the treatment of cancer types resistant to the EZH2 orthostericinhibitors." (PMID 34351144, 2021). "Targeting EZH2 is among one of the most promising epigenetic therapies in cancer treatment but has not yet been evaluated in PanNEN." (PMID 34638497, 2021). "In addition to EZH2, HDAC, and IDH inhibitors, targeting DNMT is also a potential strategy for cancer therapy." (PMID 34054126, 2021). "However, some signaling proteins were found to be common regulatory molecules among the three cancers whereas terminal enzymes, such as EZH2, ENO2, RRM2, and TYMS, were found to be commonly regulated in all the cancers by three different regulatory mechanisms." (PMID 34790674, 2021). "EZH2, a catalytic subunit of the PRC2 complex, is another PcG protein involved in cancer." (PMID 33804165, 2021). "Moreover, the small-molecule inhibitors of EZH2, Tazemetostat, and CPI-1205 are currently tested in clinical trials, targeting the overexpression of EZH2, observed in several cancer types." (PMID 33430434, 2021). "In this study, the EZH2 inhibitor GSK126 can significantly inhibit the methylation level of histone H3, prevent the proliferation of PC cells in vitro and in vivo, and promote the expressions of apoptosis-related protein to aggravate apoptosis of cancer cells." (PMID 34335707, 2021). "EZH2 gene is highly expressed in a variety of malignant tumors but is low or not expressed in normal tissues." (PMID 34604069, 2021). "Further, we showed that EZH2 was indeed highly expressed in cancer tissues, but the prognosis of patients was not affected by the expression of EZH2, which was consistent with the conclusion of the previous study." (PMID 34671029, 2021). "Emerging evidence has suggested that EZH2 also plays some unconventional roles in cancers, such as functioning as a non-histone protein transmethylase or a PRC2-independent transcriptional factor." (PMID 34737746, 2021). "Indeed, estrogen-resistant cancer cells overexpress HER2, which results in the constitutive activation of BCL2 by inactivating EZH2 through the AKT pathway." (PMID 33478063, 2021). "Finally, we combined the EZH2 inhibition with AMPK, known to be highly expressed in E.C.M. detached cancer cells and observed antagonistic effects between the two pathways." (PMID 33531586, 2021). "EZH2 and SUZ12 are the primary epigenetic mediators expressed at high levels in cancer stem cells." (PMID 33805687, 2021). "Functionally antagonistic roles of EZH2 and SWI/SNF have previously been demonstrated, leading to the hypothesis that targeting EZH2 in SWI/SNF mutant cancers could be effective due to synthetic lethality." (PMID 34439236, 2021). "Furthermore, we determined that EZH2 inhibitors induce ERVs, LINE-1 and an interferon response in a variety of cancer types." (PMID 34966479, 2021). "While some cancers are dependent on both paralogs, others are dependent only on EZH2, leading to the development of both selective and nonselective catalytic inhibitors." (PMID 34617019, 2021). "Data on both EZH2 and CD8 immunohistochemistry was available for 1075 cancers." (PMID 32303902, 2021). "EZH2 (Enhancer of zeste homolog 2), a catalytic component of polycomb repressive complex 2 (PRC2), methylates lysine 27 of histone H3 to promote transcriptional silencing and is an important drug target for controlling cancer via epigenetic processes." (PMID 34358125, 2021).
cancer (continued). "Alternatively, YY1 could recruit enzymes able in turn to modify the chromatin (es., EZH2, HDAC) and, hence, orchestrate changes in the epigenetic status of the BCL2L15 gene, as it was observed in other cancer and non-cancer models." (PMID 34445183, 2021). "Given the many ongoing clinical trials of EZH2 and EZH1/2 inhibitors in a variety of cancers including HCC38, the combined use of epigenetic therapeutic agents, such as UNC1999, may prove useful to treat patients with advanced HCC." (PMID 34725436, 2021). "Although more and more studies have shown that EZH2 was closely related to human cancer, no pan-cancer analysis is available." (PMID 34381492, 2021). "In our cohort, nearly all cases with an SDC component of carcinoma ex PA expressed EZH2, whereas the PA component showed almost no expression of EZH2." (PMID 35186711, 2021). "NSC745885 treatment downregulated expression of the enhancer of zeste homolog 2 (EZH2) in cancer cells, but not SV-HUC-1 cells." (PMID 32880874, 2020). "Clearly, cancer cells frequently gain genetic alterations, leading to increased EZH2 levels, and thus increasingly rely on EZH2’s noncanonical functions for malignant growth." (PMID 33327550, 2020). "Hence, the epigenetic modifier EZH2 expression has been found altered in ERMS and SS, where it appears to support a less differentiated and more aggressive phenotype and cancer survival." (PMID 32532153, 2020). "The insertion of the 3-bromo-4-hydroxybenzylidene portions at the 3,5 positions of the 1-benzylpiperidin-4-one yielded 2, inactive against PRMT1, SET7, and p300 HAT, and exhibiting selective inhibition of CARM1 and EZH2 (unpublished results), a KMT highly involved in cancer diseases." (PMID 32650558, 2020). "EZH2 is one of the EMT features and having important role in cancer progression." (PMID 31897240, 2020). "EZH2 inhibitory drugs may abrogate pro-oncogenic features of PRC2 and turn the balance to cell differentiation via SWI/SNF activity in cancers." (PMID 33230143, 2020). "Many members of PcG family play important roles in cancer, including Bmi-1, Mel-18, CBX7, and EZH2." (PMID 32723346, 2020). "The histone methyltransferase EZH2, the catalytic subunit of PRC2, has been confirmed to promote the trimethylation of H3K27 (H3K27me3), which is involved in the epigenetic silencing of target genes during cancer development." (PMID 32885590, 2020). "Furthermore, overexpression of HMGA1Ps lead to increase of HMGA2, and other cancer related proteins such as VEGF and EZH2." (PMID 33126409, 2020). "Another important point highlighted by these studies is that EZH2 and H3K27me3 levels do not always correlate in certain cancer types." (PMID 33050946, 2020). "Histone deacetylases (HDACs), histone methyltransferases (HMTs as EZH2) and the family of BET (bromodomain and extra-terminal domain) seem to be the most involved in the cancer process, but histone acetyltransferases (HATs) and histone demethylases (HDMs) can also be deregulated in cancers." (PMID 32708698, 2020). "Besides the stem cells, the increasing evidence has proved that EZH2, being a catalytic subunit of PRC2 plays a key role in metabolic process in cancer cells as well, directly or indirectly." (PMID 32448308, 2020). "As the master epigenetic regulator, enhancer of zeste homolog 2 (EZH2) suppresses gene transcription mainly by catalyzing the trimethylation of histone H3 at lysine 27 (H3K27me3) and exerts highly enzymatic activity in cancer cells." (PMID 32448308, 2020). "Overall, the existing literature suggests EZH2’s noncanonical roles to be more evident in cancer where EZH2 frequently shows overexpression due to various genomic alterations, such as genomic loss of EZH2-targeting miRNAs." (PMID 33327550, 2020). "CEP55, EZH2, and SLCA11 are highly expressed in HCC and play critical regulatory roles in cancers." (PMID 32104698, 2020).
cancer (continued). "This was not the case in cancers with serous histology, where significantly lower EZH2 levels were found in low-grade serous (LGSOC), as compared with high-grade serous OCs (P < 0.001);." (PMID 33230143, 2020). "This implies that EZH2 may have a different substrate(s) other than H3K27 and may be driving oncogenesis through non-H3K27me3-mediated processes in these cancer types." (PMID 33050946, 2020). "This study suggests a novel miR-33b/MYC/EZH2 axis that modulates the growth and the progression of breast cells and could be clinically useful to design new drugs against HER2+ subtype cancer." (PMID 33014831, 2020). "Further, while ACTG1 gain was found to be associated with increased PRC2 activity, EZH2, a core member of the PRC2 complex and an oncogenic target in several cancers was not altered in the same patient samples." (PMID 33217970, 2020). "Interestingly, and similarly to migration and invasion in cancer, many lncRNAs have also been identified that form complexes with EZH2 and DNMT proteins in the apoptosis process of cancer." (PMID 33050646, 2020). "Because EZH2 deregulation is prevalent in human diseases such as cancer, there is increased dependency on its noncanonical function, which shall have important implications in developing more effective therapeutics." (PMID 33327550, 2020). "As observed in cancer cells, TALE treatment also caused a decreased expression of Ezh2, Lsd1, Dnmt1, β-catenin, and Smad proteins in NPCs, but not a decreased Hdac1." (PMID 31130994, 2019). "Our results provide an explanation for the paradoxical dual role of EZH2 and PRC2 in cancer." (PMID 31468686, 2019). "The connection between the differential anti-cancer efficacies of EZH2 inhibitor in PTEN-positive versus PTEN-negative cancer cells with FOXO1 protein induction and cellular localization further highlights the essential role of FOXO1 in EZH2 inhibitor-induced death of cancer cells." (PMID 31410199, 2019). "This suggests that either EZH2 and STAT3 do not co-localize on chromatin when EZH2 methylates STAT3, or that EZH2 does not coordinate with STAT3 in the brain as it does in cancer cells." (PMID 31891591, 2019). "Third, UCA1 overexpression could promote cancer metastasis by activation of metastasis-related genes including GRK2/ERK-MMP9, EZH2/AKT, p21/E-cadherin, iASPP, KLF4-KRT6/13, FGFR1/ERK and ZEB1/2-FSCN1." (PMID 30918102, 2019). "Moreover, combined inhibition of EZH2, LSD1, HDACs, and DNMTs in cells of different cancer types led to post-mitotic neuron-like terminal differentiation, an effect resembling differentiation of neural progenitor/stem cells into post-mitotic neurons." (PMID 31130994, 2019). "EZH2-DANCR mechanism can also be found in many cancers: In non-small-cell lung cancer cells, it promotes cell proliferation, migration, and invasion by inhibiting p21 expression." (PMID 31799189, 2019). "We therefore hypothesised that whilst complementary functions of EZH2 and EMX2 ensure controlled self‐renewal of normal cells, cancer cells may benefit from EMX2 silencing to unlock unrestrained proliferation." (PMID 31468686, 2019). "Inhibition of Ezh2 could reverse Doc-induced expression of Nanog, Sox2, CD44 and Doc-induced enriched population of cancer stem cells." (PMID 30621625, 2019). "We also show that EZH2 plays a key role in the maintenance of stability of its interaction partners, via interaction with deubiquitase USP7, so as to maintain a network promoting cancer initiation and progression." (PMID 31130994, 2019). "UNC1999 was shown to be able to reduce H3K27me3 levels as well as cell proliferation in a large number of cancer cells, without affecting EZH2 protein level." (PMID 31619182, 2019). "Also, when combined with UNC1999, an inhibitor of EZH2 or JQ1, a BET bromodomain inhibitor, PTC-209 exhibited both synergistic and additive effects in MM (INA-6, JJN3, RPMI-8226, and LP-1) cancer cell lines." (PMID 31695609, 2019).
cancer (continued). "Consistent with this, codeletion of Ezh2 and Snf5 is not compatible with cancer development in mice." (PMID 31123059, 2019). "In recent years, the non-canonical role of EZH2 as a transcriptional co-activator has been demonstrated in several types of cancer." (PMID 31752930, 2019). "Indeed, a few small molecule inhibitors of EZH2, such as GSK126, have been developed to target the methyltransferase activity of EZH2 for cancer treatment 14-16." (PMID 31410199, 2019). "Altogether, our data show that EZH2 cooperates with E2F1 to stimulate expression of genes involved in ACC aggressiveness and establishes RRM2 as an interesting therapeutic target in this cancer." (PMID 31363169, 2019). "In light of several studies showing that p57 is a target of EZH2, the PRC2 catalytic subunit, in different cancer cell types and in differentiating Schwann cells, we focused our attention on the tri-methylation of lysine 27 in histone H3 (H3K27me3), the modification catalyzed by this complex." (PMID 30651140, 2019). "Some of them were reported to be cancer-related genes, such as CCNB1, EZH2, AXIN2, and FOXF2." (PMID 31321712, 2019). "In the past few years, enhancer of zeste homolog 2 (EZH2), the catalytic subunit of Polycomb repressive complex 2 (PRC2), has aroused broad research interest because of its multiple roles in the development of many types of cancer." (PMID 31921860, 2019). "In order to identify EZH2 target genes in ACC, we performed correlation analyses on the basis of publicly available transcriptome data from Cochin, Michigan and TCGA cohorts, which represented a total of 146 cancer patients." (PMID 31363169, 2019). "The expressions of OGT and EZH2 proteins in three cancer breast cell lines (MCF7, T47D and MDA-MB-231) and one non-neoplastic breast cell line (MCF10A) were compared." (PMID 29864144, 2018). "While most studies have focused on the role of EZH2 as a transcriptional repressor in cancer, there is mounting evidence that EZH2 has non-canonical functions involving transcriptional activation and methylation of non-histone proteins." (PMID 30022044, 2018). "Even if the principal activity of EZH2 as a gene silencer proceeds through the methylation of H3K27, a large number of studies have shown that the transcriptional activation of EZH2 in many types of cancer is achieved independently of H3K27me." (PMID 30510924, 2018). "The examined molecules include major class I and II histone deacetylases (HDACs), histone demethylases LSD1, JMJD2A and JMJD2D, histone methyltransferases EZH1, EZH2 and G9a, and DNA methyltransferase DNMT1, most of which have been shown to be deregulated in cancer cells." (PMID 29464084, 2018). "As EZH2 is thought to be a critical regulator of cell migration/invasiveness higher expression of EZH2 in more aggressive cancer cells than less aggressive and non-tumorigenic cells was expected." (PMID 29864144, 2018). "P27kip, a gene coding a tumor suppressor protein involved in cell cycle arrest via the inhibition of CDK proteins, presented an EZH2-dependent repression of transcription in MIA-PaCa2 and Panc04.03 cancer cells, leading to uncontrolled cell growth and aggressiveness." (PMID 34991274, 2018). "UNC1999, an EZH2 specific inhibitor, was successful in all three of these model systems, not only reducing aberrant K27 methyl marks that characterize PDAC cells, but also slowing proliferation rates of the cancer cells." (PMID 29710783, 2018). "Although these compounds are still being evaluated, it appears that EZH2 inhibition is a very promising therapeutic approach in a wide range of cancer types (solid tumors or not)." (PMID 34991274, 2018). "Therefore, the characterization of the role of EZH2 and KDM6B during EMT should provide new possibilities for designing anti-cancer therapeutic approaches." (PMID 34991274, 2018).